ANXA7 (annexin A7)
Diseases named in the same sentence as ANXA7 in open-access papers (continued):
Sharing a sentence is not in itself a finding about the gene and the disease.
glioblastoma (13 papers, 2013 to 2025). The most malignant astrocytic tumor (WHO grade IV). "When there is a loss of ANXA7 serving as a tumor suppressor in glioblastoma, this yields to poor control of EGFR signaling and results in a poorer prognosis for the patient." (PMID 38639785, 2024). "ANXA7 has been shown to downregulate EGFR in glioblastoma and loss of ANXA7 mRNA expression was associated with poor survival and prognosis in glioblastoma patients." (PMID 36247003, 2022). "Moreover, loss of ANXA7 is associated with prognosis in glioblastoma patients, and ANXA7 is a strong predictor of patient outcome." (PMID 32922940, 2020). "Moreover, loss of Anxa7 tumor suppressor expression with gain in epidermal growth factor receptor protein induced survival signaling pathway and reported earlier, demonstrated to be a high risk factor in evaluating the survival of glioblastoma patient." (PMID 24550987, 2014). "Loss of ANXA7 function stabilizes the EGFR protein, augments EGFR transforming signaling in glioblastoma cells, and promotes tumorigenesis." (PMID 35800363, 2022). "ANXA7 expression has been reported an independent outcome predictor in glioblastoma multiforme, and its expression correlated with longer survival in patients with GBM." (PMID 36247003, 2022). "In humans, annexin A7 appears to have a tumour-suppressive role in some forms of cancer (e.g., glioblastoma), but in others, it seems to promote malignancy (e.g., gastric cancer)." (PMID 33572113, 2021). "We found the total mRNA levels of EGFR and four EGFR transcripts were dramatically reduced after PTBP1 stable knockdown, which in agreement with previous study that PTBP1 stablized mRNA of EGFR by inhibiting ANXA7-mediated EGFR degradation in glioblastoma." (PMID 28404950, 2017). "The 47 kDa isoform of Annexin A7 is expressed in astrocyte-derived C6 rat glioblastoma cells, which is in contrast to human brain tissues." (PMID 24188284, 2013). "Immunofluorescence also showed the co-localization of UBE3C and ANXA7 in glioblastoma cells." (PMID 26067607, 2015). "Available data indicate that ANXA7 might function as a tumor-suppressor gene in glioblastoma." (PMID 38639785, 2024). "In glioblastoma, PTBP1 promotes glioblastoma progression by mediating annexin A7 exon splicing, eliminating its tumor suppressor functions." (PMID 36508323, 2023). "Treatment of glioblastoma cells with MA led to the inhibition of GSK3 kinase, resulting in the downregulation of SRSF1/5, PTPB1, and hnRNP with decreased levels of anti-apoptotic genes such as BCL2, BCL-xL, Survivin, MCL1, and BMI1 while increased in Anxa7, a tumor suppressor gene." (PMID 39863145, 2025).
gastric cancer (8 papers, 2013 to 2022). A primary or metastatic malignant neoplasm involving the stomach. "Loss of ANXA7 expression has been associated with distant metastases in gastric cancer, hence suggesting an oncosuppressor role." (PMID 36247003, 2022). "ANXA7 expression was also found to be downregulated along gastric cancer progression and inversely correlated with apoptosis." (PMID 36247003, 2022). "Study showed that ANXA7 inhibition suppressed the growth of gastric cancer cells in vitro and in vivo and promote their apoptosis." (PMID 32526706, 2020). "In gastric cancer, the significance of ANXA7 expression remains controversial." (PMID 36247003, 2022). "However, other studies have pointed to a protumor role of ANXA7 in gastric cancer." (PMID 36247003, 2022). "In Yuan’s study on gastric cancer, the survival rate of patients with positive expression of annexin A7 was lower than that of patients with negative expression." (PMID 34484309, 2021).
glioma (8 papers, 2014 to 2024). A benign or malignant brain and spinal cord tumor that arises from glial cells (astrocytes, oligodendrocytes, ependymal cells). "Here we have observed splicing deregulation with elevated Anxa7 VA (variant) transcript with loss in Anxa7 VB (WT) in comparison with Normal Brain cDNA Clontech company in U87 and U373 glioma cells." (PMID 24550987, 2014). "On the contrary, the ubiquitin-protein ligase E3C (UBE3C) led to the ubiquitination and degrading of Annexin A7, promoting glioma development." (PMID 34106407, 2021). "Next, we evaluated the correlation between UBE3C and ANXA7 mRNA and protein expression in 12 cases of glioma tissues by linear correlation analysis." (PMID 26067607, 2015). "IHC assay also showed that UBE3C protein expression positively correlated with low ANXA7 protein expression in glioma tissues, and vice versa." (PMID 26067607, 2015). "Our study clearly shows that high UBE3C expression contributes to glioma progression by ubiquitination and degradation of ANXA7, and thus presents a novel and promising target for future glioma therapies." (PMID 26067607, 2015). "Another important finding from present study was that UBE3C promoted glioma progression through formation of a complex with ANXA7 and ubiquitination and degradation of ANXA7." (PMID 26067607, 2015). "Earlier we have shown that Anxa7 is a EGFR negative regulator; its allelic loss has been depicted with enhanced glioma survival signaling pathway." (PMID 24550987, 2014). "Thus, our data reveal that high UBE3C expression contributes to glioma progression by ubiquitination and degradation of ANXA7, and thus presents a novel and promising target for glioma therapy." (PMID 26067607, 2015). "Importantly, the inhibition of ANXA7 expression in gliomas cells with UBE3C interference could rescue the cell invasion." (PMID 26067607, 2015). "Our results also revealed that increased UBE3C expression was accompanied by a reduction in ANXA7 protein expression in glioma tissues, but not ANXA7 mRNA." (PMID 26067607, 2015). "In reciprocal co-IP assays, we showed that UBE3C formed a complex with ANXA7 in 293T cells, and the significantly negative correlation of both proteins in glioma samples." (PMID 26067607, 2015).
hepatocellular carcinoma (8 papers, 2019 to 2025). A malignant tumor that arises from hepatocytes. "Annexin A7 (ANXA7), originally named synexin, was the first annexin to be discovered four decades ago15 and has since been associated with tumor progression and reduced overall survival in cancers including hepatocellular carcinoma and breast cancer." (PMID 31040365, 2019). "It has been demonstrated that the ethanolic extract of Phyllanthus nanus upregulates ANXA7 expression in HBV-infected hepatoma cells, which correlates with suppressed HBV replication and reduced HBsAg secretion." (PMID 40717977, 2025). "ANXA7 promotes the proliferation, migration and invasion of lymphatic metastatic cells from hepatocellular carcinoma and inhibits their apoptosis." (PMID 36936694, 2023). "In hepatocellular carcinoma, ANXA7 can promote the proliferation and migration of HCC through the MAPK/ERK signalling pathway." (PMID 33397392, 2021). "This represents the first study reporting that LEPR promoted proliferation, migration, and invasion and inhibited apoptosis in hepatocellular carcinoma by regulating ANXA7." (PMID 33397392, 2021). "In our laboratory, we used immunoprecipitation combined with mass spectrometry to identify proteins that interact with ANXA7 in mouse hepatoma cells, including LEPR (unpublished data)." (PMID 33397392, 2021). "Previous studies have found that the JNK/ANXA7 signaling pathway is expressed in hepatocellular carcinoma cells." (PMID 32775428, 2020). "In this study, we explored whether LEPR promotes proliferation, migration, and invasion and inhibits apoptosis in hepatocellular carcinoma by regulating ANXA7." (PMID 33397392, 2021). "In this study, we screened for lncRNAs regulated by ANXA7 and JNK in hepatoma cells by RNA sequencing of stable ANXA7 and JNK knockdown cell lines and conducted bioinformatics analyses to identify species with a high probability of involvement in cancer-related cellular processes." (PMID 32775428, 2020). "In hepatocellular carcinoma (HCC), ANXA7 silencing inhibited the proliferation and migration of HCC through the MAPK/ERK signaling pathway." (PMID 32526706, 2020). "ANXA7 was reported to promote EMT, contributing to hepatocellular carcinoma aggressiveness." (PMID 40022181, 2025). "ANXA7 knockdown reduces mRNA, the protein levels of LEPR and the intracellular signalling pathways of the ERK1/2, JAk2/STAT3 and PI3K-related proteins, thereby promoting apoptosis in hepatocellular carcinoma." (PMID 36936694, 2023). "Knockdown of Annexin A7 (ANXA7) or C-Jun N-terminal kinase (JNK) inhibits the proliferation, migration, invasion, and lymphatic adhesion of hepatocellular carcinoma (HCC) cells, suggesting that ANXA7 and JNK signaling pathways contribute to HCC growth and lymph node metastasis (LNM)." (PMID 32775428, 2020).
liver cancer (6 papers, 2019 to 2022). An epithelial or non-epithelial malignant neoplasm that arises from the liver. "ANXA7, a Ca2+-binding protein that is involved in membrane organization and dynamics, plays a role in promoting the proliferation of liver cancer, and a loss of function decelerates the proliferation of liver cancer." (PMID 36346805, 2022). "It has also been confirmed that RACK1 and ANXA7 are interacting proteins that participate in liver cancer metastasis." (PMID 31474227, 2019). "ANXA7 modulates the growth, differentiation, proliferation, secretion, invasion, migration, and apoptosis of various tumor cells and is a key regulator of early-stage hepatic cancer lymphatic metastasis in mice." (PMID 32775428, 2020).
colorectal cancer (5 papers, 2008 to 2021). A primary or metastatic malignant neoplasm that affects the colon or rectum. "The expression profile of these annexins was then validated on a large cohort of well-characterised colorectal cancer samples, and the immunohistochemical component of the study was also extended to include a further annexin, annexin A7, as it has also been implicated in tumorigenesis." (PMID 18071363, 2008). "From our current study, we found a significant upregulation of annexin A7 protein expression in HCT 116 cells treated with GS, indicating that GS treatment in this colorectal cancer cells leads to increased expression of annexin A7 and is positively correlated with apoptosis." (PMID 31581454, 2019).
melanoma (4 papers, 2019 to 2022). A malignant, usually aggressive tumor composed of atypical, neoplastic melanocytes. "On the other hand, supporting a tumor-suppressor role, ANXA7 has been pointed as a marker for a less invasive phenotype in melanoma." (PMID 36247003, 2022). "ANXA7 might act as a tumour suppressor gene in prostate, melanoma and glioblastoma cancer." (PMID 33397392, 2021).
Anxiety (3 papers, 2021 to 2023). Intense feelings of nervousness, tension, or panic often arise in response to interpersonal stresses. "Defects in intracellular Ca2+ regulation may in fact underlie phenotypic manifestations in ANXA7 (+/−) mice, ranging from neoplasia to anxiety." (PMID 37240163, 2023).
diabetes (3 papers, 2013 to 2022). "The data allowed us to build models that could distinguish DKD from diabetes (AUC = 0.928) with 2 proteins (ALB, AFM), and distinguish DKD3 from DKD4 (AUC = 0.949) with 3 proteins (ANXA7, APOD, C9)." (PMID 34963468, 2021).
metastatic tumors (3 papers, 2012 to 2025). "On the other hand, we suggest that drug combinations targeting ANXA3/ANXA6, and ANXA11/ANXA7 might be useful against lung- and liver-metastatic diseases, respectively." (PMID 40410902, 2025). "The stable knockup and knockdown of Annexin A7-expressing HCC cells using Annexin A7 cDNA and shRNA vectors, respectively, were injected into a mouse footpad to establish primary and metastatic tumors in mice." (PMID 24188284, 2013).
pancreatic cancer (3 papers, 2012 to 2025). "BAG4 has been found to be overexpressed in pancreatic cancer and positively correlated with ANXA7, HSP70 and BCL-2." (PMID 40870378, 2025).
atherosclerosis (2 papers, 2014 to 2018). A disease characterized by the build-up of fatty material and calcium deposition in the arterial wall resulting in partial or complete occlusion of the arterial lumen. "Recent studies have shown that ANXA7 plays a very important role in atherosclerosis, other cardiovascular diseases, and a variety of tumors." (PMID 29896083, 2018). "ANXA7 also participated in the progression of atherosclerosis and targeting ANXA7 inhibited atherosclerosis in apoE−/− mice." (PMID 24864152, 2014). "A recent study showed that ANXA7, having different roles in autophagy, tumor suppression, and exocytosis, was negative regulation of PC-PLC in HUVECs and suggested that ANXA7/PC-PLC signaling pathway may present a novel target to treat atherosclerosis." (PMID 24864152, 2014). "ANXA7/PC-PLC signaling pathway may represent a novel target for the treatment of atherosclerosis." (PMID 24864152, 2014). "Considering the important roles of ANXA7 and PC-PLC in atherosclerosis and propolis modulated atherosclerosis and affected PC-PLC activity, we hypothesized that propolis may also affect ANXA7, the endogenous regulator of PC-PLC." (PMID 24864152, 2014). "In present study we tested the hypothesis by investigating the effects of Chinese propolis and Brazilian green propolis on PC-PLC activity and ANXA7 level in ox-LDL-stimulated HUVECs; ox-LDL plays crucial role in triggering the development of atherosclerosis." (PMID 24864152, 2014).
COVID-19 (2 papers, 2020 to 2022). A disease caused by infection with severe acute respiratory syndrome coronavirus 2. "Analyzing the lung bronchoalveolar lavage fluid scRNA-seq data from patients with severe COVID-19 outcomes shows macrophages, lung epithelial cells, T-cells, club cells, proliferating cells, and plasma cells are significant expressors of ANXA7." (PMID 33024578, 2020). "Taken together with the HLA-B*40:01 restricted binding of the PAM and ANXA7 peptides mimicked by SARS-CoV-2, the ALOX5AP splicing variant also mimicked by SARS-CoV-2 suggests the possibility of immune evasion or autoinflammation in HLA-B*40-constrained COVID-19 patients." (PMID 33024578, 2020).
dyslipidemia (2 papers, 2014 to 2021). "In present study, the data indicated that both Chinese propolis and Brazilian green propolis reduced PC-PLC activity and increased ANXA7 level in ox-LDL-stimulated endothelial cells, which suggested that ANXA7/PC-PLC might be the targets of both types of propolis in modulating dyslipidemia." (PMID 24864152, 2014).
hematoma (2 papers, 2022 to 2023). A hematoma is a collection of blood from a vascular structure into an extravascular space. "Serum ANXA7 levels were strongly correlated with NIHSS scores (P < 0.001), hematoma volume (P < 0.001), and GCS scores (P < 0.001); serum ANXA7 levels were significantly raised with increasing ICH scores (P < 0.001)." (PMID 36003296, 2022). "Using multivariate analysis, it is revealed that rising serum ANXA7 levels are dramatically related to NIHSS scores and hematoma volume, as well as END and 90-day unfavorable outcome after ICH." (PMID 36003296, 2022). "Using multivariate analysis, serum annexin A7 levels >57.4 ng/ml independently predicted END after adjustment for intraventricular hemorrhage, NIHSS scores, hematoma volume, and GCS scores." (PMID 36003296, 2022). "Using multivariate analysis, serum ANXA7 levels above 57.0 ng/ml were retained as the independent predictor of post-injury 90-day unfavorable outcome after adjustment for age, intraventricular hemorrhage, NIHSS scores, hematoma volume, and GCS scores." (PMID 36003296, 2022). "Serum ANXA7 levels were independently correlated with NIHSS score [beta: 0.821; 95% confidence interval (CI): 0.106–1.514; variance inflation factor: 5.180; t = 2.573; P = 0.014] and hematoma volume (beta: 0.794; 95% CI: 0.418–1.173; variance inflation factor: 5.281; t = 2.781; P = 0.007)." (PMID 36003296, 2022).
lymph node metastasis (2 papers, 2008 to 2013). "This disparity illustrates that the Annexin A7 gene plays an important role in high and low lymph node metastasis." (PMID 24188284, 2013). "The annexins except annexin A7 showed immunoreactivity in lymph node metastasis." (PMID 18071363, 2008).
Stroke (2 papers, 2022). Sudden impairment of blood flow to a part of the brain due to occlusion or rupture of an artery to the brain. "This is the first series to ascertain whether serum ANXA7 levels are associated with stroke severity and clinical outcome of ICH." (PMID 36003296, 2022). "Overall, serum ANXA7 may be a promising biochemical variable for assessing stroke severity and predicting clinical outcome." (PMID 36003296, 2022). "Benzoxazine derivate reduces lesion size in atheroprone mice, but could AnxA7 inhibitors be beneficial in myocardial infarction or stroke?" (PMID 36313572, 2022).
subarachnoid hemorrhage (2 papers, 2021 to 2022). A serious neurological disorder characterized by intracranial hemorrhage into the subarachnoid space. "In rats with subarachnoid hemorrhage, ANXA7 knockdown markedly reduced early brain injury via alleviating disruption of blood–brain barrier, ameliorating brain edema, and depressing neuronal apoptosis." (PMID 36003296, 2022). "ANXA7 knockdown dramatically decreased glutamate release from injured brain tissues in rats with subarachnoid hemorrhage." (PMID 36003296, 2022). "High expression of ANXA7 was intimately related to the poor neurological status of subarachnoid hemorrhage rats." (PMID 36003296, 2022). "Also, ANXA7 protein expression was enhanced markedly at 24 h following experimental subarachnoid hemorrhage." (PMID 36003296, 2022). "Similar results were also obtained after subarachnoid hemorrhage-induced brain injury and correlate with elevated AnxA7 levels in traumatic brain injury, making AnxA7-based therapies a potentially novel and alternative approach in the treatment of cerebrovascular disease." (PMID 33810523, 2021).
asthma (1 paper, 2024). "Proteins TCN2,TNFRSF1B and C10orf54 were positively associated with the development of asthma (B>0); proteins PDGFD,INHBC and ANXA7 were negatively associated with the development of asthma (B<0)." (PMID 39318474, 2024).
bladder cancer (1 paper, 2021). "ANXA1, ANXA2, ANXA3, ANXA5, ANXA6, ANXA7, and ANXA9 had prognostic value in bladder cancer." (PMID 34484309, 2021).
bladder tumor (1 paper, 2021). "ANXA2, ANXA3, ANXA4, ANXA8, and ANXA9 were significantly increased in bladder tumor tissues, while ANXA6, ANXA7, and ANXA11 were significantly decreased." (PMID 34484309, 2021).
brain infarction (1 paper, 2025). Tissue necrosis in any area of the brain, including the cerebral hemispheres, the cerebellum, and the brain stem. "Further tests showed that administration of AnxA2, AnxA5, AnxA6, or AnxA7 to the healthy mouse brain caused brain CaP deposition, as tested by the Alizarin Red S assay, in association with brain infarction, as detected by the TTC assay." (PMID 39820937, 2025).
cardiac hypertrophy (1 paper, 2022). "Genes associate with cardiac hypertrophy included JMJD1C, ANXA7, TRIM8, NGB, and AKAP13." (PMID 36071494, 2022).
Crohn's colitis (1 paper, 2022). Crohn's disease affecting the colon. "In conclusion, this study suggests that circGMCL1 protects intestinal barrier function against Crohn’s colitis through alleviating NLRP3 inflammasome-mediated epithelial pyroptosis by promoting autophagy through regulating ANXA7 via sponging miR-124-3p." (PMID 36088391, 2022). "This study suggests that circGMCL1 protects intestinal barrier function against Crohn’s colitis through alleviating NLRP3 inflammasome-mediated epithelial pyroptosis by promoting autophagy through regulating ANXA7 via sponging miR-124-3p." (PMID 36088391, 2022).
Duchenne muscular dystrophy (1 paper, 2021). Duchenne muscular dystrophy (DMD) is a neuromuscular disease characterized by rapidly progressive muscle weakness and wasting due to degeneration of skeletal, smooth and cardiac muscle. "However, the localization of ANXA7 has been shown to be altered in myofibers of patients with Duchenne muscular dystrophy." (PMID 34067866, 2021).